COX6B1 (cytochrome c oxidase subunit 6B1)
Description:
Component of the cytochrome c oxidase, the last enzyme in the mitochondrial electron transport chain which drives oxidative phosphorylation. The respiratory chain contains 3 multisubunit complexes succinate dehydrogenase (complex II, CII), ubiquinol-cytochrome c oxidoreductase (cytochrome b-c1 complex, complex III, CIII) and cytochrome c oxidase (complex IV, CIV), that cooperate to transfer electrons derived from NADH and succinate to molecular oxygen, creating an electrochemical gradient over the inner membrane that drives transmembrane transport and the ATP synthase. Cytochrome c oxidase is the component of the respiratory chain that catalyzes the reduction of oxygen to water. Electrons originating from reduced cytochrome c in the intermembrane space (IMS) are transferred via the dinuclear copper A center (CU(A)) of subunit 2 and heme A of subunit 1 to the active site in subunit 1, a binuclear center (BNC) formed by heme A3 and copper B (CU(B)). The BNC reduces molecular oxygen to 2 water molecules using 4 electrons from cytochrome c in the IMS and 4 protons from the mitochondrial matrix.
Synonyms: COX6B; COXG; COXVIb1; MC4DN7
Tractability: Small molecule: a structure with a bound ligand is known. Antibody: UniProt places it where antibodies can reach, with high confidence. PROTAC: ubiquitination databases record sites on it; its protein half-life has been measured.
Gene: Protein-coding gene on chromosome 19 (35,648,230 to 35,658,795, forward strand). Ensembl gene ENSG00000126267.
Subcellular location: Mitochondrion inner membrane
Subcellular location (Human Protein Atlas): Mitochondria; Principal piece
Pathways (Reactome):
Metabolism: Complex IV assembly; Respiratory electron transport
Cellular responses to stimuli: Cytoprotection by HMOX1
Gene Ontology:
Molecular function: cytochrome-c oxidase activity
Biological process: substantia nigra development; cellular respiration; mitochondrial electron transport, cytochrome c to oxygen; oxidative phosphorylation; proton transmembrane transport
Cellular component: mitochondrial inner membrane; mitochondrial membrane; mitochondrion; respiratory chain complex IV; membrane
Genetic constraint (gnomAD): Loss-of-function variants: 2 observed, 14.97 expected, observed/expected ratio (o/e) 0.13, 90% interval 0.054 to 0.42. The upper end of that interval is the gene's LOEUF score, 0.42, which puts it in group 1 of 6, group 1 being the genes least tolerant of losing a copy. Missense variants: 81 observed, 119.84 expected, observed/expected ratio (o/e) 0.68, 90% interval 0.56 to 0.81. Synonymous variants: 30 observed, 41.93 expected, observed/expected ratio (o/e) 0.72, 90% interval 0.53 to 0.97.
Gene-disease validity (ClinGen):
ClinGen rates the evidence that COX6B1 causes each of these diseases.
mitochondrial disease (autosomal recessive): Definitive.
Homologues: Orthologues: chimpanzee COX6B1 (100% identical), guinea pig COX6B1 (86% identical), mouse Cox6b1 (84% identical), macaque COX6B1 (80% identical), rat Cox6b1 (76% identical), Caenorhabditis elegans cox-6B (42% identical). Paralogues in human: COX6B2 (53% identical).
Diseases named in the same sentence as COX6B1 in open-access papers:
COX6B1 is named in the same sentence as 45 diseases in open-access papers, as found by Europe PMC text mining. Sharing a sentence is not in itself a finding about the gene and the disease. The quoted sentences say what the papers report.
cardiomyopathy (4 papers, 2022 to 2025). A disease of the heart muscle or myocardium proper. "A deficiency in mitochondrial complex IV, which can be caused by mutations in COX6B1, has been linked with hydrocephalus, encephalomyopathy, and cardiomyopathy." (PMID 39902331, 2025). "COX6B1, a mitochondrial gene, was previously reported to be associated with encephalomyopathy, hydrocephalus, and cardiomyopathy." (PMID 38419527, 2024).
Hydrocephalus (4 papers, 2023 to 2025). Hydrocephalus is an active distension of the ventricular system of the brain resulting from inadequate passage of CSF from its point of production within the cerebral ventricles to its point of absorption into the systemic circulation. "In addition, recent research has reported that COX6B1 dysregulation could have significant effect on the COX functions, possibly resulting into the development of hydrocephalus, cerebromyopathy and other disorders." (PMID 38259479, 2023).
lung adenocarcinoma (4 papers, 2022 to 2025). A carcinoma that arises from the lung and is characterized by the presence of malignant glandular epithelial cells. "Another study has shown that LncRNA SNHG15 competes with COX6B1 to bind miR-30b-3p through a ceRNA mechanism to affect proliferation, migration, and invasion of lung adenocarcinoma cells." (PMID 41365992, 2025). "miR-30b-3p acts as a tumor suppressor gene in lung adenocarcinoma, and it can inhibit the proliferation and invasion of lung adenocarcinoma by targeting the expression of COX6B1." (PMID 36002193, 2022). "COX6B1 could be targeted by miRNA-30b to inhibit the proliferation and invasion in lung adenocarcinoma." (PMID 38698303, 2024). "EdU cell proliferation assay and Transwell invasion assay showed that the overexpression of miR-30b-3p could reverse the promoting effect of upregulation of COX6B1 on proliferation and invasion in lung adenocarcinoma cells (P<0.05)." (PMID 36002193, 2022).
lung carcinoma (3 papers, 2024 to 2025). "The genes Fubp1, Cox6b1, Pon3, Iars2, Ctsd, and Akr1b1 have been previously shown to promote lung cancer proliferation." (PMID 39273313, 2024). "Druggability evaluation suggests that existing drugs targeting ITGB2, GP1BA, ACADSB and COX6B1 could potentially be repurposed for the treatment of specific lung cancer subtypes." (PMID 41340014, 2025). "Additionally, the repurposing of approved drugs targeting ITGB2, GP1BA, ACADSB and COX6B1 for the treatment of different lung cancer subtypes provides new therapeutic options, potentially leading to more effective treatments for patients with advanced lung cancer." (PMID 41340014, 2025). "According to our previous transcriptomic analysis, PAH and lung cancer have three (C1QBP, COX6B1, and SLC12A8) common overregulated genes located in the transmembrane helix related to negative regulation of transcription by RNA polymerase II and chemical carcinogenesis-reactive oxygen species." (PMID 39791702, 2024).
mitochondrial encephalomyopathy (3 papers, 2014 to 2025). A heterogenous group of disorders characterized by alterations of mitochondrial metabolism that result in muscle and nervous system dysfunction. "Mutation in Cox6b1 causes mitochondrial encephalomyopathy due to Cox deficiency." (PMID 24598864, 2014).
Parkinson disease (3 papers, 2011 to 2021). A progressive degenerative disorder of the central nervous system characterized by loss of dopamine producing neurons in the substantia nigra and the presence of Lewy bodies in the substantia nigra and locus coeruleus. "This analysis revealed that the genes implicated in Parkinson’s disease (Atp5a1, Ndufa7, Ndufb2, Ndufs8, Park7, Cox7a2, Cox7c, Cox6b1, Cycs, Uchl1) were upregulated in thia-exposed mice (p-value = 4.2E-3)." (PMID 34295895, 2021). "Second, and more interesting, the oxidative phosphorylation chain, including seven genes (ATP5C1, ATP6AP1, ATP6V1H, COX5B, COX6B1, NDUFA1, and UQCRC1), five of them shared with Huntington's and Parkinson's disease KEGG categories." (PMID 21541025, 2011).
cardiac hypertrophy (2 papers, 2021). "Network analysis mapping protein–protein interactions and synergistic actions of AR using multi-component networks reveal drug targets such as ACADM, COX4I1, COX6B1, HBB, MYH14, and SLC25A4, as potential pharmacological co-targets for cardiac hypertrophy." (PMID 33589646, 2021).
liver disease (2 papers, 2020 to 2025). "The subunit of cytochrome-c-oxidase 6B1, COX6B1, is linked to liver disease, ATP synthesis, electron transport, and gene expression." (PMID 40901642, 2025).
myocardial ischemia (2 papers, 2019 to 2022). A disorder of cardiac function caused by insufficient blood flow to the muscle tissue of the heart. "Our results show that over-expression of COX6B1 could effectively restrain cell apoptosis during myocardial ischemia." (PMID 30311029, 2019).
bile acid synthesis disorder (1 paper, 2025). "Druggability evaluation highlighted four protein biomarkers, ITGB2, GP1BA, ACADSB and COX6B1, which are already targeted for dry eye disease, inflammation, seizure and bile acid synthesis disorder, respectively." (PMID 41340014, 2025).
cervical cancer (1 paper, 2014). A primary or metastatic malignant neoplasm involving the cervix. "Other genes, such as COX6B1 is related to cell apoptosis and ESRRA also have been reported associated with cervical cancer." (PMID 24992025, 2014).
cognitive decline (1 paper, 2024). "Two of these genes, COX6B1 and KMT2B, are involved in monogenic childhood-onset neurological disorders with cognitive decline and delayed motor or cognitive development." (PMID 38811690, 2024).
dyslipidemia (1 paper, 2020). "Some of the DE proteins predicted to affect mitochondrial function also cause dyslipidemia, including MECR, CS, ACLY, AOX3, and COX6B1 by RIS, and CYCS, COX6B1, and ENO3 by OLAN." (PMID 33302598, 2020).
epilepsy (1 paper, 2022). A brain disorder characterized by episodes of abnormally increased neuronal discharge resulting in transient episodes of sensory or motor neurological dysfunction, or psychic dysfunction. "The mitochondrial enzyme COX6B1 had the largest fold change in both SUDC and epilepsy, which was decreased in both groups." (PMID 35333953, 2022).
esophageal cancer (1 paper, 2021). A primary or metastatic malignant neoplasm involving the esophagus. "Using The Cancer Genome Atlas database, we analyzed the relationships of NDUFA1, NDUFS5, and COX6B1 expression with esophageal cancer." (PMID 34226508, 2021).
Hypertension (1 paper, 2024). The presence of chronic increased pressure in the systemic arterial system. "For example, proteins important for vascular structure (FLNA) and calcium regulation (ACTN4) were up-regulated, and mitochondrial function (COX6B1) was down-regulated, in human hypertension." (PMID 38879891, 2024).
hypertrophic cardiomyopathy (1 paper, 2021). A condition in which the myocardium is hypertrophied without an obvious cause. "Mutation in the gene corresponding to COX6B1 protein, where histidine is replaced by cysteine at R20 residue, leads to reduced expression of COX6B1 protein in muscle and fibroblasts causing hypertrophic cardiomyopathy or cardiac muscle dysfunction." (PMID 33589646, 2021).
laryngeal squamous cell carcinoma (1 paper, 2021). A squamous cell carcinoma that arises from the larynx. "COX6B1, as one of the core proteins involved in the molecular basis of the below-background radiation stress response, might inhibit the proliferation of laryngeal squamous cell carcinoma cells." (PMID 34901000, 2021).
leukemia (1 paper, 2025). A malignant (clonal) hematologic disorder, involving hematopoietic stem cells and characterized by the presence of primitive or atypical myeloid or lymphoid cells in the bone marrow and the blood. "Further, CRISPR targeting of these COX4I1‐regulated Complex IV members (such as COX5A, COX6B1, etc.)also exhibits a selective impact on blood cancer cells, emphasizing a unique addiction of leukemia cells to the intact functional Complex IV." (PMID 39716856, 2025).
lymph node metastasis (1 paper, 2012). "Two SNPs in COX6B1 (complex IV) were associated with lymph node metastasis in a dominant model (rs6510502, OR = 1.75, 95% CI 1.20–2.57; rs10420252, OR = 1.68, 95% CI 1.11–2.53); rs6510502 was associated also with distant metastasis (OR = 1.67, 95% CI 1.09–2.56 in a dominant model)." (PMID 22545919, 2012). "Added to that, the two studied polymorphisms in COX6B1 (complex IV), rs6510502 in the promoter and rs10420252 in the 5′-UTR, were associated with lymph node metastasis, and rs6510502 also with distant metastasis." (PMID 22545919, 2012).
microphthalmia (1 paper, 2023). Congenital or developmental anomaly in which the eyeballs are abnormally small. "A similar search of DR17 using the term microphthalmia resulted in 22 genes significant for the small eyes phenotype: Aldh1a3, Aff4, Bmp4, Cdk4, Cox6b1, Cxcr4, Dync1li1, Eef1d, Fgd1, Gne, Grh12, Mab21l2, Maf, Med13l, Mllt10, Mthfd2, Pex6, Phgdh, Ssr1, Stim1, Tdo2, and Vps26c." (PMID 36737727, 2023).
small cell lung carcinoma (1 paper, 2025). Small cell lung cancer (SCLC) is a highly aggressive malignant neoplasm, accounting for 10-15% of lung cancer cases, characterized byrapid growth, and early metastasis. "For small cell lung cancer, ACADSB, CEACAM6, COX6B1, CPXM2 and IL12RB2 continued to show significant associations." (PMID 41340014, 2025). "Our study identified five candidate proteins for small cell lung cancer: ACADSB, CEACAM6, COX6B1, CPXM2 and IL12RB2." (PMID 41340014, 2025).
viral infection (1 paper, 2025). "Mitochondrial components, including the inner and outer membranes, were highly enriched (e.g. ATP5MC3, COX6B1 and SLC25A38; adjusted P<0.01), underscoring the role of mitochondrial reprogramming during viral infection." (PMID 40989927, 2025).
cancer (4 papers, 2021 to 2025). A tumor composed of atypical neoplastic, often pleomorphic cells that invade other tissues. "For malignant cells, consistently upregulated metabolic genes were predominantly associated with cancer hallmark pathways, including glycolysis (GAPDH, GPI and LDHA), OXPHOS (COX6B1 and ATP5MC2), and nucleotide metabolism (TK1, GUK1, NME1)." (PMID 39393173, 2024). "Remarkably, the oncogenes shown are Known to decrease apoptosis that could result in cancer cell survival like YBX1, SNRPE, RRM2, and COX6B1." (PMID 41347211, 2025).
neurodegenerative disease (2 papers, 2022 to 2025). A disorder of the central nervous system characterized by gradual and progressive loss of neural tissue and neurologic function. "The prioritized genes and pathways, particularly the YWHAZ neuronal-glial axis and the Ecdysterone-COX6B1 interaction, represent compelling targets for future research aimed at developing novel interventions for neurodegenerative diseases." (PMID 41296471, 2025). "For example, COX4I1 and COX6B1 enriched in the neurodegenerative disease pathway are two subunits of cytochrome c oxidase, are an integral part of the mitochondrial machinery needed for ATP production in mammalian cells, and are found to be overexpressed when neuronal cells are injured." (PMID 36188472, 2022).
tumor (2 papers, 2021). "The results indicated that cloperastine inhibited tumor growth was by suppressing NDUFA1, NDUFS5, and COX6B1 expression." (PMID 34226508, 2021).
COX6B1 also shares sentences with these, for which no sentence is quoted: encephalomyopathy (3 papers); neurological diseases (2); adenocarcinoma (1); Alzheimer disease (1); asthenospermia (1); asthma (1); blood cancer (1); brain diseases (1); COVID-19 (1); cyst (1); heart failure (1); Huntington disease (1); infection (1); kidney cancer (1); myocarditis (1); pituitary adenomas (1); preeclampsia (1); small cell carcinoma (1); squamous cell carcinoma (1).